PARPBP (PARP1 binding protein)
Description:
Required to suppress inappropriate homologous recombination, thereby playing a central role DNA repair and in the maintenance of genomic stability. Antagonizes homologous recombination by interfering with the formation of the RAD51-DNA homologous recombination structure. Binds single-strand DNA and poly(A) homopolymers. Positively regulate the poly(ADP-ribosyl)ation activity of PARP1; however such function may be indirect.
Synonyms: PARI; C12orf48; FLJ20641; AROM
Tractability: PROTAC: ubiquitination databases record sites on it.
Gene: Protein-coding gene on chromosome 12 (102,120,122 to 102,197,531, forward strand). Ensembl gene ENSG00000185480.
Subcellular location: Cytoplasm; Nucleus
Subcellular location (Human Protein Atlas): Nucleoplasm
Gene Ontology:
Molecular function: protein binding
Biological process: negative regulation of double-strand break repair via homologous recombination
Cellular component: chromatin; nucleoplasm; nucleus; cytoplasm
Genetic constraint (gnomAD): Loss-of-function variants: 10 observed, 10.44 expected, observed/expected ratio (o/e) 0.96, 90% interval 0.59 to 1.6. The upper end of that interval is the gene's LOEUF score, 1.6, which puts it in group 6 of 6, group 1 being the genes least tolerant of losing a copy. Missense variants: 251 observed, 252.42 expected, observed/expected ratio (o/e) 0.99, 90% interval 0.9 to 1.1. Synonymous variants: 91 observed, 94.51 expected, observed/expected ratio (o/e) 0.96, 90% interval 0.81 to 1.15.
Homologues: Orthologues: chimpanzee PARPBP (99% identical), macaque PARPBP (95% identical), dog PARPBP (82% identical), rabbit PARPBP (82% identical), pig PARPBP (79% identical), guinea pig PARPBP (69% identical), mouse Parpbp (69% identical), rat Parpbp (54% identical), tropical clawed frog parpbp (46% identical), zebrafish parpbp (36% identical).
Diseases named in the same sentence as PARPBP in open-access papers:
PARPBP is named in the same sentence as 17 diseases in open-access papers, as found by Europe PMC text mining. Sharing a sentence is not in itself a finding about the gene and the disease. The quoted sentences say what the papers report.
hepatocellular carcinoma (3 papers, 2020 to 2022). A malignant tumor that arises from hepatocytes. "PARPBP has been demonstrated to be a negative regulator of homologous recombination and to be involved in cell cycle regulation and contribute to unfavorable outcomes in hepatocellular carcinoma." (PMID 32133296, 2020). "PARPBP, a significant inhibitor of homologous recombination (HR), has been demonstrated to be related to increased AFP levels, proliferation, differentiation, and poor prognosis of lung and hepatocellular carcinoma patients." (PMID 34568334, 2021).
colorectal cancer (2 papers, 2021 to 2025). A primary or metastatic malignant neoplasm that affects the colon or rectum. "In colorectal cancer, KIF18B has been observed to interact with SP1, resulting in the upregulation of PARPBP and the maintenance of oxaliplatin resistance in oxaliplatin-resistant colorectal cancer (OR-CRC) cells." (PMID 40110038, 2025). "Next, we detected the expression and distribution of PARPBP, KNSTRN, and KIF2C in colorectal cancer and performed a multiplex immunofluorescence staining in TMAs." (PMID 34568334, 2021).
gastric cancer (2 papers, 2020 to 2022). A primary or metastatic malignant neoplasm involving the stomach. "Moreover, PARPBP has been suggested to be activated by FOXM1 in gastric cancer cells." (PMID 32133296, 2020).
myeloid leukemia (2 papers, 2022). A clonal proliferation of myeloid cells and their precursors in the bone marrow, peripheral blood, and spleen. "PARPBP overexpression is associated with hyperproliferation in pancreatic cancers, hepatocellular carcinoma, and myeloid leukemia." (PMID 35181635, 2022).
gastric tumor (1 paper, 2022). "Through IHC analysis, we found in gastric tumor tissues (n = 10) that the protein expression of most of the genes in the DRGS, except for PARPBP, EME1, and RAD54L, was significantly increased." (PMID 35676932, 2022).
lung carcinoma (1 paper, 2021). "PARPBP promotes tumor cell migration and invasion by enhancing mutagenic replication, extravasation, anoikis resistance, and self-renewal in lung cancer." (PMID 34568334, 2021).
ovarian carcinoma (1 paper, 2022). A malignant neoplasm originating from the surface ovarian epithelium. "Besides, SNORA70E also regulates the alternative splice of PARPBP to promote the development of ovarian cancer." (PMID 36056690, 2022). "In conclusion, SNORA70E promotes the occurrence and development of ovarian cancer through pseudouridylation modification of RAP1B and alternative splicing of PARPBP." (PMID 36056690, 2022).
rectal cancer (1 paper, 2021). A primary or metastatic malignant neoplasm that affects the rectum. "The prognostic index formula for colon and rectal cancer patients in the training cohorts was as follows: Risk score = [Status of PARPBP ∗ (-0.6921)] + [Status of KNSTRN ∗ (1.4204)] + [Status of KIF2C ∗ (-0.9696)]." (PMID 34568334, 2021).
tumor (7 papers, 2012 to 2025). "Specifically, overexpression of SNORA70E enhances tumour cell propagation, invasion, and migration in vitro, driving tumour progression via pseudouridylation of RAP1B and alternative splicing of PARPBP in ovarian cancer." (PMID 39834094, 2025).
cancer (5 papers, 2012 to 2025). A tumor composed of atypical neoplastic, often pleomorphic cells that invade other tissues. "C12orf48, also named PARP1 binding protein, is over-expressed in several cancers." (PMID 35100974, 2022). "Parp1 binding protein (PARPBP) is an important component of DNA replication and damage response pathways and is differentially expressed in various cancers." (PMID 35181635, 2022).
PARPBP also shares sentences with these, for which no sentence is quoted: breast carcinoma (3 papers); pancreatic cancer (3); infertile (2); autoimmune disease (1); ischemia (1); lung adenocarcinoma (1); pancreatic ductal adenocarcinoma (1).